LRRK2 (leucine rich repeat kinase 2)
Diseases named in the same sentence as LRRK2 in open-access papers (continued):
Sharing a sentence is not in itself a finding about the gene and the disease.
neurodegenerative disease (continued). "Next, we combined the 833 participants in a single population set and compared the burden of protein-altering variants between T1R-affected vs T1R-free participants for PRKN, LRRK2, and 22 additional PD-linked genes included in the neurodegenerative disease panel." (PMID 41430073, 2025). "Nevertheless, the findings from the present study indicate that LRRK2 hyper-kinase is critically involved in Mn’s neurotoxicity and other neurodegenerative diseases associated with LRRK2 hyper-kinase activity through dysregulation of autophagy and inflammasome." (PMID 37269951, 2023). "Nonetheless, Mn-induced LRRK2 activation in microglia could be a potential target for treating Mn toxicity and other neurodegenerative diseases associated with elevated LRRK2 function." (PMID 37269951, 2023). "Mutations in leucine-rich repeat kinase 2 (LRRK2) are a major cause of familial and sporadic Parkinson’s disease (PD), a neurodegenerative disease characterized by selective loss of dopaminergic neurons in the substantia nigra pars compacta region of the midbrain." (PMID 32057291, 2020). "In addition, both CD4+ and CD8+ T cells of PD patients expressing higher levels of inflammatory cytokines also expressed higher levels of LRRK2 suggesting that LRRK2 protein expression is associated with the inflammatory response characteristically seen in this neurodegenerative disease." (PMID 28649611, 2017). "LRRK2 mutations exhibit a variety of pathological characteristics which include α-synuclein, ubiquitin, and tau protein inclusions leading to the suggestion that LRRK2 may be an important upstream modulator of protein aggregation in neurodegenerative disease." (PMID 23028814, 2012). "The biological significance of LRRK2 is underscored by its link to neurodegenerative diseases, most notably Parkinson's disease (PD)." (PMID 41065010, 2026). "Overall, we have identified a potential link between lysosomes, LRRK2 kinase activity and neuronal vulnerability to pathological protein accumulation across neurodegenerative diseases." (PMID 40661559, 2025). "Furthermore, mutations in LRRK2 have been found to impact the production of neurotrophic factors in astrocytes, the star-shaped glial cells of the central nervous system, thereby affecting neuronal health and contributing to the pathology of neurodegenerative diseases like PD." (PMID 40309866, 2025). "The α-Syn-mediated neurotoxicity, as one mainstay of research fields in neurodegenerative diseases, has been strongly correlated with LRRK2, but it should be worked on its exact mechanism." (PMID 40629324, 2025). "Leucine-rich repeat kinase 2 (LRRK2) is a multifunctional protein kinase intricately involved in the pathogeneses of various neurodegenerative diseases, particularly Parkinson’s disease (PD)." (PMID 40309866, 2025). "Given that both loss of LRRK2 function and the kinase-activating LRRK2 G2019S mutation disrupt the endolysosomal system, uptake of additional cargoes relevant to neurodegenerative disease were analysed in the different LRRK2 genotypes." (PMID 40790356, 2025). "The activation of TLRs by LRRK2 promotes a cycle of neuroinflammation that accelerates neurodegenerative diseases." (PMID 40309866, 2025). "Novel treatments are urgently needed to protect neurons from neurodegenerative diseases, including PD, and LRRK2 has emerged as a promising drug target." (PMID 38275734, 2024). "LRRK2–PD microglia as well as microglia from other neurodegenerative diseases additionally displayed increased phagocytic activity, paralleling our finding in IFNγ treated SPG11 iMGL." (PMID 38305941, 2024). "It has garnered significant interest in neurodegenerative disease research, particularly due to its phosphorylation by the LRRK2 kinase." (PMID 40535172, 2024).
neurodegenerative disease (continued). "Collectively, these results indicated that E. coli could specifically drive the progression of sPD with LRRK2 risk variants, which further suggested that the specific genetic risk variants and their corresponding environmental factors mightsynergistically contribute to neurodegenerative diseases." (PMID 38010914, 2023). "Pathogenic mutations in the leucine-rich repeat kinase 2 (LRRK2) gene are frequent causes of familial Parkinson’s Disease (PD), an increasingly prevalent neurodegenerative disease that affects basal ganglia circuitry." (PMID 36358985, 2022). "The abnormal structure of the pathogenic proteins such as LRRK2, Tau, HTT and the aggregation of specific proteins such as polyQ and α-Syn can be the hallmarks of neurodegenerative diseases and have great potential in precision medicine." (PMID 37288246, 2022). "Mn is also thought to stimulate microglia, releasing inflammatory cytokines and causing upregulation of leucine-rich repeat kinase 2 (LRRK2), which is involved in various neurodegenerative diseases." (PMID 33072457, 2020). "This indicates that LRRK2 plays a role in various neurodegenerative diseases, warranting further investigation to advance our understanding of LRRK2-related pathology." (PMID 30645642, 2019). "In this study we have identified several potential candidates for further research on drugs to treat neurodegenerative diseases related to LRRK2, NMDA, and TrkA proteins." (PMID 30044400, 2018). "This, coupled with the previously established importance of autophagy in a number of neurodegenerative diseases, has focussed current research on the role of LRRK2 during the autophagic process." (PMID 24710487, 2012). "Because CHIP has been shown to regulate cellular levels of other proteins linked to neurodegenerative disease, such as phospho-tau, we investigated the effect of CHIP overexpression on levels of LRRK2." (PMID 19536328, 2009). "We sought to determine whether Rab12 phosphorylation mediated by LRRK2 is altered in neurodegenerative diseases with tau and/or α-synuclein pathology." (PMID 40661559, 2025). "This suggests that pS106-Rab12 labeling of GVBs is consistently observed across neurodegenerative diseases with tau pathology, regardless of LRRK2 mutation status." (PMID 40661559, 2025). "In this study, we tested whether aberrant LRRK2 activity is associated with tau and/or α-synuclein pathology in clinically distinct neurodegenerative diseases by analyzing LRRK2-mediated phosphorylation of Rab12 at amino acid Ser106 (pS106-Rab12)." (PMID 40661559, 2025). "In neurodegenerative diseases, studies targeting CK to regulate upstream LRRK2 activity could be of relevant interest given this close connection of these kinases both involved in CNS pathogenesis." (PMID 39519213, 2024). "Given the key roles of LRRK2 and CKs in the development of neurodegenerative diseases, clarifying their interaction link could be important for the search for new diagnostic and therapeutic markers of these pathologies." (PMID 39519213, 2024). "Given the prominence of LRRK2 pathology in PD pathogenesis, LRRK2 may also play a role in other neurodegenerative diseases such as ischemia, traumatic brain injury and AD." (PMID 30645642, 2019). "Previously 14–3-3 proteins have been implicated in interactions with several proteins associated with PD including α-synuclein, Parkin and LRRK2 and targeting 14–3-3 PPI using small molecules offers a promising strategy for PD and other neurodegenerative diseases." (PMID 30819229, 2019). "The increase in connection with LRRK2-PD and other neurodegenerative diseases might be a response to increased production of active radicals in connection with the disease process and thus a protective mechanism against neuronal loss." (PMID 26357583, 2015).
neurodegenerative disease (continued). "Considering both pathological α-synuclein and tau accumulation induce endolysosomal stress, and both proteins can be degraded by lysosomes, LRRK2 and Rab12 may play fundamental roles in mediating early stages of α-synuclein and tau pathology in neurodegenerative diseases." (PMID 40661559, 2025). "Therefore, based on all this scientific evidence, the overexpression of LRRK2 in neuronal and glial inclusions in numerous neurodegenerative diseases suggests that these pathologies may share a common pathophysiological pathway." (PMID 39519213, 2024). "Based on the growing knowledge of neuron–glia interactions in homeostasis, aging and neurodegenerative diseases, it is possible that glial cells could, in part, contribute to the accelerated phenotypes and impaired behavior observed in LRRK2 G2019S transgenic mice." (PMID 30927072, 2019). "Lastly, PSEN2 Thr421Met may interact with other mutations in neurodegenerative disease related genes, which were found in the proband patient, such as ATP binding cassette subfamily A member 7 (ABCA7), Notch Receptor 3 (NOTCH3), or Leucine-rich repeat kinase 2 (LRRK2)." (PMID 36362122, 2022). "Interestingly, expression of several non-ISG, non-immune genes was reduced in uninfected Lrrk2 KO BMDMs, including ApoE, which has been repeatedly linked to inflammatory and neurodegenerative diseases, and Ldhb, a critical metabolic gene involved in post-glycolytic energy production." (PMID 32057291, 2020). "Concomitantly, 14-3-3 proteins are physiological “inhibitors” of several kinases whose dysregulation is involved in cancer and neurodegenerative diseases (e.g., RAF, ASK1, LRRK2)." (PMID 33233473, 2020). "Next, we examined the levels of LRRK2 mRNA and protein in postmortem brains from patients with CTE, a neurodegenerative disease found in people who had multiple head injuries." (PMID 30420654, 2018). "In conclusion, LRRK2 is an important gene in the context of neurodegenerative diseases, and non-rodents provide a highly useful model for exploring the pathogenetic mechanisms associated with this gene." (PMID 40076730, 2025). "Furthermore, leucine-rich repeat kinase 2 (LRRK2) and myocyte enhancer factor 2D (MEF2D) have been identified as typical CMA substrates in neurodegenerative diseases." (PMID 38472355, 2024). "Current evidence is also supportive of the hypothesis that LRRK2 activity is essential for REM/NREM sleep stability and SD-related cognition, which is mediated by microglial synaptic refinement in neurodegenerative diseases." (PMID 36138936, 2022). "Along with V180I mutations in PRNP, genetic variations in other genes, such as lipoprotein(a) (LPA), Leucine-rich repeat kinase 2 (LRRK2), and fibroblast growth factor 20 (FGF20), which are directly or indirectly related to neurodegenerative diseases, were also observed in patients with V180I gCJD." (PMID 31238786, 2019). "These two regions were selected, because SN is an important brain area to investigate in some neurodegenerative diseases, particularly in PD, while, OCTX showed the highest expression level of LRRK2 between the other 10 brain regions in our previous microarrays study." (PMID 30223621, 2018). "We have demonstrated that LRRK2 is localized to both brainstem LBs in idiopathic PD and cortical LBs in DLB, indicating that LRRK2 is indeed an essential component of the LBs in these two neurodegenerative diseases." (PMID 17137507, 2006). "This perspective is beginning to be adopted by the field with respect to genes implicated in the endolysosomal system including leucine-rich repeat kinase (LRRK2), progranulin (GRN), and glycoprotein non-metastatic B (GPNMB) as risk genes for several neurodegenerative diseases." (PMID 38883776, 2024). "Therefore, understanding the role of LRRK2 and CK1 and their crosstalk in neurodegenerative diseases could be important for the development of new therapeutic approaches." (PMID 39519213, 2024).
cancer (82 papers, 2010 to 2026). A tumor composed of atypical neoplastic, often pleomorphic cells that invade other tissues. "Concerning the genetic subgroups, 8.04% of the LRRK2 mutation carriers had a positive cancer history (16 patients out of 199)." (PMID 41300754, 2025). "Some reports suggest that individuals with the G2019S LRRK2 variant face an elevated risk of cancers of the blood, brain, and breast." (PMID 41300754, 2025). "In comparisons of iPD and genetic PD subgroups, LRRK2 carriers demonstrated a significantly increased cancer risk." (PMID 41300754, 2025). "Compared to iPD, LRRK2 carriers had an increased general cancer risk (RR 1.26), particularly brain (RR 2.41), breast (RR 2.57), colon (RR 1.83) and hematological cancers (RR 2.05)." (PMID 40243562, 2025). "Intriguingly, several previous studies have demonstrated that LRRK2 G2019S mutation carriers have an overall elevated risk of cancer, especially hormone-related cancers, and breast cancer in women." (PMID 38607004, 2024). "Previous studies have provided evidence that individuals carrying the LRRK2 G2019S mutation are at an increased risk of developing cancers." (PMID 38607004, 2024). "On the other hand, according to a previous epidemiological study, PD patients with the LRRK2 G2019S mutation displayed a greater global cancer risk." (PMID 37629650, 2023). "A comparison of subsequent cancer risk in LRRK2-G2019S PD and idiopathic PD patients revealed that LRRK2-G2019S PD patients had an increased risk of cancer in general (RR = 1.26, 95% CI = 1.09–1.46)." (PMID 35247252, 2022). "Subgroup analysis comparing cancer risk after PD diagnosis in LRRK2-G2019S mutation carriers and idiopathic PD patients included six studies." (PMID 35247252, 2022). "It is therefore unsurprising to find increased cancer risks amongst LRRK2-G2019S PD patients in our study, with LRRK2 promoting PD-associated neurodegeneration and cancer-related pathogenesis pathways." (PMID 35247252, 2022). "Overall, further studies are needed to detail the underlying mechanisms by which LRRK2 is regulated following DNA damage and contributes to HR‐mediated DNA repair in cancers." (PMID 33784003, 2021). "The increased risk for cancer among LRRK2 carriers was mainly driven by the association between harboring the mutation and breast cancer, observed in women." (PMID 33584195, 2021). "Recently, accumulating evidences have proposed that LRRK2 mutations are highly associated with cancers." (PMID 33784003, 2021). "We obtained our data from the national Cancer Registry of Norway and we calculated data and cancer outcomes from 857 sporadic PD patients and 76 LRRK2 mutation carriers." (PMID 33584195, 2021). "LRRK2 mutation carriers have an increased risk of cancer, especially for hormone-related cancer, and SCLC is associated with polypeptide hormone production." (PMID 33880365, 2021). "Individuals with the most common pathogenic LRRK2 mutation, G2019S, have been reported to have an increased risk of developing cancers although this is disputed." (PMID 31864390, 2019). "While some examples below highlight neurodegenerative pathways as examples of inactivation by phosphorylation, further cancer-focused work needs to be undertaken to extend these mechanisms as both Cdk5 and LRRK2 activity have been implicated in cancer." (PMID 30678096, 2019). "Assessing the cancer risk in different LRRK2 mutation types is an interesting path, as the various mutations “affect the formations and activity of the protein LRRK2 in different and specific ways” yet ultimately lead to the same phenotype." (PMID 29568677, 2018). "Demographic data and cancer outcomes from 830 iPD patients and 103 LRRK2 mutation carriers (27 with PD) were retrospectively collected." (PMID 29568677, 2018). "A Kaplan–Maier survival analysis was conducted to estimate survival curves for age at cancer diagnosis for both LRRK2 mutation carriers and iPD‐patients." (PMID 29568677, 2018).
cancer (continued). "LRRK2 has also been linked to cancer, with the PD G2019S mutation associated with specific cancers such as non-skin and hormonal cancers and the R1441C mutation linked to increased risk of colon cancer." (PMID 29308544, 2018). "In conclusion, this study confirms increased cancer risk in LRRK2 mutation carriers compared with iPD subjects." (PMID 29568677, 2018). "The PINK1 and LRRK2 somatic mutations identified in cancer were all heterozygous and their pathological effect remains to be determined." (PMID 21203498, 2010). "Notably, female PD patients harboring pathogenic LRRK2 variants demonstrated a significantly increased overall cancer risk compared to female iPD patients as well." (PMID 41300754, 2025). "Mutations in LRRK2 have also been linked to an increased risk of cancer." (PMID 36716346, 2023). "LRRK2 gene is involved in a variety of cellular processes including cell transformation, proliferation and tumorigenesis, and is linked to various types of cancer." (PMID 33658398, 2021). "The LRRK2 p.G2019S activating mutation has also been associated with an increased risk of cancer." (PMID 30678096, 2019). "The most important limitation to this study, and the majority of studies assessing the association between harboring a LRRK2 mutation and developing cancer, is the retrospective screening of cancer outcomes in comparing risk of cancer in iPD versus LRRK2 mutation carriers." (PMID 29568677, 2018). "However, the statistical power to investigate associations between the LRRK2 mutation and uncommon cancers was limited by the relatively small sample size and small number of some cancers." (PMID 29568677, 2018). "Several studies have assessed the cancer frequency in LRRK2‐associated PD." (PMID 29568677, 2018). "Human genetics has linked LRRK2 to PD, Crohn’s disease, multibacillary leprosy, and cancer." (PMID 30562929, 2018). "Still the underlying mechanism linking LRRK2 and cancer remains to be elucidated." (PMID 29568677, 2018). "In addition to these, LRRK2 could play a role in cancer, given the identification of LRRK2 variants associated with different types of carcinomas." (PMID 37698513, 2023). "In addition, as LRRK2 mutation carriers have been the focus of most LRRK2-related epidemiological studies of cancer incidence, an overactive LRRK2 phenotype was presupposed; consequently, to our knowledge, a role for LRRK2 loss in cancer pathogenesis has yet to be considered, including for LUAD." (PMID 33483550, 2021). "In addition, as centrosomal alterations are frequently associated with cancer, the changes reported here may further contribute to the reported increased cancer risk in LRRK2 PD patients." (PMID 29357897, 2018). "Intriguingly, in a cancer-type dependent manner, LRRK2 appears to affect tumor development -both promoting and suppressing them- by affecting crucial cellular pathways." (PMID 39744510, 2025). "The distinctive contribution of this study lies in its examination of genetic forms of PD—including carriers of LRRK2, GBA1, SNCA, PRKN, and PINK1 mutations—in relation to cancer risk." (PMID 41300754, 2025). "Particularly, the expression of INHBA, HSP90AA1 and EIF2AK2 in ESCC cancer tissues was significantly higher than that in normal tissues, while the level of LRRK2 and HSPB8 in ESCC tissues was remarkably lower as compared to the normal tissues." (PMID 39006030, 2024). "For instance, mutations in genes such as SNCA (α-synuclein), ATM (ataxia telangiectasia mutated), PARK2 (parkin), PARK8 (LRRK2), MC1R (Melanocortin 1 receptor) and PTEN (Phosphatase and tensin homolog) have been identified in both PD and certain cancers." (PMID 39563740, 2024). "For example, Muthene revealed the synergistic effects of apoptosis and necroptosis caused by Vincristine and Dasatinib, respectively, and the additive effect exerted by LRRK2, an unexpected cancer target indirectly modulated by Vincristine." (PMID 36562724, 2023).